ADAM33 (ADAM metallopeptidase domain 33)
Description:
Metalloprotease that cleaves and sheds the ectodomains of cell-surface proteins and thereby contributes to angiogenesis, cell differentiation, inflammation, and cell proliferation. Modulates the activity of adhesion molecules and cytokines by generating soluble forms, leading to either attenuation of cell-surface signaling or initiation of downstream intracellular signaling pathways. For instance, acts as a constitutive sheddase of kit ligand/KITLG. Promotes and maintains a proliferative phenotype in vascular smooth muscle cells through regulation of the PI3K/AKT and ERK signaling pathways. Additionally, enhances cell migration and regulates cytokine secretion during airway vascular remodeling via the same signaling cascades.
Synonyms: C20orf153; DKFZp434K0521; dJ964F7.1
Tractability: Small molecule: a structure with a bound ligand is known; a high-quality ligand is known; it belongs to a druggable protein family. Antibody: UniProt predicts a signal peptide or a membrane-spanning region; the Human Protein Atlas places it where antibodies can reach. PROTAC: a small molecule that binds it is known.
Target class: Metallo protease MAM clan; Metallo protease; Protease; Enzyme; Metallo protease M12B subfamily
Gene: Protein-coding gene on chromosome 20 (3,667,962 to 3,682,246, reverse strand). Ensembl gene ENSG00000149451.
Subcellular location: Cell membrane
Subcellular location (Human Protein Atlas): Plasma membrane; Nuclear speckles
Pathways (Reactome):
Cell-Cell communication: Regulation of CDH11 function
Gene Ontology:
Molecular function: metalloendopeptidase activity; zinc ion binding; metallopeptidase activity
Biological process: proteolysis
Cellular component: membrane; plasma membrane
Genetic constraint (gnomAD): Loss-of-function variants: 104 observed, 94.83 expected, observed/expected ratio (o/e) 1.1, 90% interval 0.94 to 1.29. The synonymous counts are far from expectation, so gnomAD's model fits this gene poorly and the ratio says little. Missense variants: 1,120 observed, 970.95 expected, observed/expected ratio (o/e) 1.15, 90% interval 1.1 to 1.21. Synonymous variants: 483 observed, 399.94 expected, observed/expected ratio (o/e) 1.21, 90% interval 1.12 to 1.3.
Homologues: Orthologues: chimpanzee ADAM33 (98% identical), macaque ADAM33 (93% identical), pig ADAM33 (75% identical), rabbit ADAM33 (74% identical), guinea pig ADAM33 (72% identical), dog ADAM33 (71% identical), mouse Adam33 (70% identical), rat Adam33 (69% identical), tropical clawed frog adam13 (48% identical), zebrafish adam19a (31% identical), Caenorhabditis elegans unc-71 (27% identical), Drosophila melanogaster mmd (19% identical). Paralogues in human: ADAM19 (42% identical), ADAM12 (39% identical), ADAM15 (37% identical), ADAM8 (33% identical), ADAM9 (31% identical), ADAM28 (29% identical), ADAM11 (28% identical), ADAM22 (28% identical), ADAM23 (26% identical), ADAM20 (26% identical), ADAM21 (26% identical), ADAM30 (25% identical), and 8 more.
Diseases named in the same sentence as ADAM33 in open-access papers:
ADAM33 is named in the same sentence as 63 diseases in open-access papers, as found by Europe PMC text mining. Sharing a sentence is not in itself a finding about the gene and the disease. The quoted sentences say what the papers report.
asthma (94 papers, 2005 to 2025). "Research has reported that ADAM33 is linked with alterations in airway structure among asthma patients, resulting in heightened responsiveness, constriction of the airways, and ultimately diminished therapeutic efficacy." (PMID 41426510, 2025). "This evidence supports the potential of ADAM33, particularly the rs2280091 variant, as a biomarker for pulmonary function progression in respiratory conditions such as asthma and CF." (PMID 41373738, 2025). "We highlight its genetic variants associated with asthma susceptibility and severity, as well as the functional effects of ADAM33 on airway remodeling, smooth muscle cell proliferation, and its interplay with environmental factors." (PMID 38396994, 2024). "This review paper focuses on the role of the ADAM33 gene in the pathogenesis, susceptibility, severity, and hypothetical treatment of asthma." (PMID 38396994, 2024). "A combined effect on the risk of developing asthma was observed with the presence of polymorphisms in the interleukin 4, β2-adrenergic receptor, and ADAM33 genes." (PMID 38396994, 2024). "The T allele for the IL-4 gene promoter (C-589T locus), the C allele frequency for ADRβ2 (Gln27Glu locus), and the A allele for the ADAM33 gene (rs2280091, T1) were higher in asthma patients than in normal individuals." (PMID 38396994, 2024). "So far, numerous studies have identified ADAM33 as a susceptibility gene for asthma and bronchial hyperresponsiveness (BHR) among multiple populations." (PMID 38396994, 2024). "We analyzed the genotype and allele frequency distribution of ADAM33 SNPs among the asthma patients classified as having severe persistent, moderate persistent, and mild persistent cases." (PMID 36766510, 2023). "ADAM33 has been associated with various asthma characteristics, such as bronchial hyperreactivity, disease progression, airway remodeling, worse lung function, and accelerated lung function decline." (PMID 36766510, 2023). "Numerous studies have shown that ADAM33 polymorphism was correlated to the risk of airway diseases, including asthma and chronic obstructive pulmonary disease (COPD)." (PMID 38071234, 2023). "ADAM33 has been linked to airway structural changes in patients with asthma, leading to airway hyperresponsiveness, narrowing, and ultimately poor treatment responsiveness." (PMID 36766510, 2023). "This study indicated that the ADAM33 SNP rs2853209 is associated with asthma and treatment responsiveness, with the minor allele conferring improved treatment responsiveness to steroids." (PMID 36766510, 2023). "The association between haplotypes of ADAM33 SNPs and asthma was obtained through a six-marker haplotype analysis using the haploview tool." (PMID 36766510, 2023). "This study aimed to evaluate the genetic association of ADAM33 SNPs with asthma, disease severity, and treatment responsiveness to ICS+LABA in the South Indian population." (PMID 36766510, 2023). "In a meta-analysis of case-control studies on associations between asthma and ADAM33, one of the first known asthma candidate genes, different polymorphisms were found among Asian and Caucasian individuals." (PMID 36011501, 2022). "Parental cognation, serum intracellular cell adhesion molecule-1, and ADAM33 were considerably linked with asthma, although the ABO blood system, IL-4, and serum E-selectin were not." (PMID 36225476, 2022). "A genome-wide evaluation of 460 Caucasian families by identified several polymorphisms within the ADAM33 gene associated with asthma susceptibility." (PMID 36292755, 2022). "The ADAM33 gene located on chromosome 20 was one of the first genes identified to be associated with asthma." (PMID 36292755, 2022). "A case-control study containing 96 asthma children and 86 healthy children showed that ADAM33 rs678881 polymorphism is significantly correlated with increased susceptibility to asthma in Chinese Han children." (PMID 34970542, 2021).
asthma (continued). "A study conducted in Columbia examined the association of the ADAM33 polymorphisms with asthma, particularly mite-specific IgE levels in the population of Caribbean coast of Colombia." (PMID 33922216, 2021). "In conclusion, the findings of this study found a significant association between multiple ADAM33 genetic polymorphisms and IgE levels, a major component in the pathophysiology of asthma." (PMID 33922216, 2021). "Some of the genes for example IL-4 receptor and ADAM metallopeptidase domain 33 (ADAM33) have been linked to asthma." (PMID 33784348, 2021). "We noticed that the ADAM33 S1 variant was in complete LD (D’) with the T1, T2, T + 1, and V4 variants among asthma adults." (PMID 33922216, 2021). "Numerous genes have been linked to the pathological process of asthma, with single-nucleotide polymorphisms (SNPs) of the ADAM33 gene being one of the most considerably reviewed." (PMID 33922216, 2021). "Previous research has shown that polymorphisms in the gene encoding for metalloprotease 33 (ADAM33) are closely associated with the risk of asthma attacks in different populations." (PMID 34607590, 2021). "Studies conducted in China and the U.S. also found a significant association between the ADAM33 V4 allele and asthma (p = 0.0001 and p = 0.032, respectively)." (PMID 33922216, 2021). "In support of the concept of an EMTU that recapitulates lung development, ADAM33, a membrane-anchored metalloprotease that is developmentally regulated, was identified as an asthma susceptibility gene by positional cloning in an outbred population." (PMID 32509793, 2020). "In this line, ADAM33 has also been associated to other allergic diseases like asthma and allergic rhinitis." (PMID 32325630, 2020). "In 2002, ADAM33 (disintegrin and metallopro-teinase domain-containing protein 33) was reported to be a genetic risk factor for susceptibility to asthma." (PMID 30186568, 2018). "ADAM33 encodes a disintegrin and metalloprotein-33 protein that participates in the bronchial remodeling process in asthma." (PMID 29588858, 2018). "The present study suggests that variations at TBXA2R and ADAM33 genes are linked with asthma susceptibility in Pakistan." (PMID 29588858, 2018). "Our results suggest that ADAM33 gene polymorphisms play a restricted role in susceptibility to asthma." (PMID 30186568, 2018). "The aim of this study was to investigate the association between four ADAM33 gene SNPs and susceptibility to asthma in patients from southwestern Iran." (PMID 30186568, 2018). "Increased risk of asthma in persons with one or more ADAM33 SNP allele(s) has been reported in African American, US white, US Hispanic, Dutch white, Icelandic, UK, and Japanese populations." (PMID 30186568, 2018). "Asthma is a complex disease, but learning more about how SNP mutations in ADAM33 give rise to asthmatic conditions will provide important clues in treating asthma." (PMID 29588858, 2018). "ADAM33 is an asthma-susceptible gene, which has been identified by positional cloning studies, that is expressed in the airway stromal cells; it is involved in airway hyperresponsiveness and is associated with decreased lung function." (PMID 29751569, 2018). "Genome-wide expression profile studies have been conducted to assess some asthma-susceptible genes that are related to smoke exposure, such as ADAM33, TNF, GSTP1, GSTM1, and GSTT1." (PMID 29751569, 2018). "ADAM33 gene polymorphisms at positions T+1 (rs2280091), T1 (rs3918396), S1 (rs2280089), and F+1 (rs511898) were examined in 150 patients with asthma and 149 age- and sex-matched healthy controls with a PCR-RFLP method." (PMID 30186568, 2018). "Although the function of these SNPs in the development of asthma is not fully understood, it is likely that the ADAM33 is an important chemokine in gene mutations that affects the pathogenesis of asthma in children." (PMID 28876365, 2017).
asthma (continued). "ADAM33 has been described in candidate gene studies to be associated with asthma and was significantly elevated in asthmatic airways." (PMID 29228930, 2017). "ADAM33 was first regarded as a susceptibility gene for bronchial hyper-responsiveness and asthma by a genome-wide linage analysis." (PMID 28876365, 2017). "In conclusion, ADAM33 polymorphisms rs2280091, rs2280090, rs2787094, rs44707 and rs528557 were significantly associated with a high risk of childhood asthma." (PMID 28876365, 2017). "This meta-analysis suggested that ADAM33 polymorphisms rs2280091, rs2280090, rs2787094, rs44707 and rs528557 were significantly associated with a high risk of childhood asthma." (PMID 28876365, 2017). "ADAM33 has been linked to allergic airway inflammation; however, its role in the pathophysiology of asthma remains to be proven." (PMID 28056993, 2017). "The present meta-analysis evaluated the relationship between ADAM33 polymorphisms and asthma risk in children." (PMID 28876365, 2017). "Results showed that in all four genetic models of ADAM33, the rs2280091 polymorphism was associated with the increased risk of childhood asthma." (PMID 28876365, 2017). "In this study, we performed a meta-analysis to examine the association between ADAM33 polymorphism and risk of asthma in children." (PMID 28876365, 2017). "Here, we report how the asthma gene a disintegrin and metalloprotease 33 (ADAM33) acts as local tissue susceptibility gene that promotes allergic asthma." (PMID 27489884, 2016). "Neither ADAM33 antibody cross-reacted with recombinant ADAM8 and ADAM12, which have been associated with asthma and show high homology with ADAM33." (PMID 27489884, 2016). "This interaction was notable in that rs910652 is located within 78 kilobases of ADAM33, which is one of the most well studied asthma susceptibility genes." (PMID 27387956, 2016). "A disintegrin and metalloprotease 33 (ADAM33) is a susceptibility gene associated with asthma and bronchial hyperresponsiveness (BHR), a finding that has been replicated in multiple populations." (PMID 27489884, 2016). "ADAM33 was the first gene to be linked to asthma susceptibility, and numerous studies have confirmed associations between this gene and asthma, although the specific causal variants are unclear and there are notable inconsistencies across studies." (PMID 27387956, 2016). "Loss of ADAM33 suppresses airway remodeling and allergic inflammation in mice, suggesting the therapeutic potential of targeting ADAM33 in asthma." (PMID 27489884, 2016). "Recent studies on epigenetic regulatory factors have further provided novel insights to the field, particularly their effect on regulation of some of the asthma susceptibility genes (e.g. methylation of ADAM33)." (PMID 27658857, 2016). "A gene encoding a disintegrin and metalloprotease (ADAM) 33 located on chromosome 20p13 was identified by positional cloning as a putative candidate gene for the development of asthma and bronchial hyperresponsiveness (BHR)." (PMID 24751681, 2014). "ADAM33 has been identified as an asthma susceptibility gene; however, the role of ADAM33 in the pathogenesis and progression of asthma remains to be elucidated." (PMID 24817794, 2014). "We and others have recently performed meta-analysis and provided further evidence that several polymorphisms in the ADAM33 are risk factors for asthma, especially in the Asian population." (PMID 24817794, 2014). "While studies have suggested that ADAM33 gene polymorphisms are important in conferring susceptibility to asthma, the data are controversial." (PMID 24817794, 2014). "For instance, Howard and colleagues assessed 8 selected ADAM33 SNPs from the original study and provided further evidence of association with asthma in four case-control asthma populations—African American (AA), US Caucasian, US Hispanic, and Dutch Caucasian." (PMID 24817794, 2014).
asthma (continued). "Significant associations between single nucleotide polymorphisms (SNPs) of the ADAM33 gene and asthma in ethnically diverse populations have been reported; however, little attention was given to rhinitis." (PMID 24751681, 2014). "Very recently, we observed that one of asthma associated ADAM33 ST+5 was significantly associated with heavy traffic, an indication of air pollution, in a total of 386 Indian individuals." (PMID 24817794, 2014). "The ADAM33 gene has been identified as a potentially important asthma candidate gene and polymorphisms in this gene have been shown to be associated with asthma and seasonal allergic rhinitis." (PMID 24751681, 2014). "Additional studies have demonstrated that single nucleotide polymorphisms (SNPs) within ADAM33 were associated with accelerated decline of lung function in the general population and in asthma patients." (PMID 25369941, 2014). "Of these, a disintegrin and metalloproteinase 33 (ADAM33) gene is the first novel susceptibility gene for asthma and airway hyperresponsiveness (AHR) identified by positional cloning and has been replicated in over 33 different population samples worldwide." (PMID 24817794, 2014). "The S2 polymorphism in ADAM33 had also been reported to be associated with asthma in many case-control studies of diverse population, including Japanese, British, and Irish, but not American, Germany, Brazilian, and Colombians." (PMID 24751681, 2014). "We and others have performed association analysis and meta-analysis and provided further evidence that several polymorphisms in the ADAM33 are risk factors for asthma, especially in the Asian population." (PMID 24817794, 2014). "In this paper, we have reviewed the studies on the replications and meta-analysis of genetic associations for ADAM33 and asthma and its related phenotypes in different populations." (PMID 24817794, 2014). "Our results support the important role of MS4A2, IL4R and ADAM33 genes in asthma and/or atopy susceptibility." (PMID 24039878, 2013). "A disintegrin and metalloprotein-33 (ADAM33) polymorphisms are important in the development of asthma and other atopic diseases." (PMID 24141861, 2013). "In the present study, five ADAM33 SNPs were associated with asthma in the study population using a different model." (PMID 24141861, 2013). "Further population and functional studies are required to elucidate the exact mechanism and functional effects of ADAM33 variants on asthma." (PMID 24141861, 2013). "The results confirmed a significant involvement of ADAM33 polymorphisms in the development of asthma in the study population." (PMID 24141861, 2013). "For example, children with variants of the ADAM33 gene are at risk for asthma, while attendance at day care in the first six months of life and the presence of older siblings appear to protect against asthma." (PMID 23762024, 2013). "We found that variants at MS4A2, IL4R and ADAM33 genes demonstrated varying association effects with the age at diagnosis of asthma, with 10 SNPs showing study-wise significance after the multiple comparison adjustment." (PMID 24039878, 2013). "In the last 20 years, >300 SNPs of ADAM33 have been identified in humans and the majority of these are associated with asthma and allergic diseases." (PMID 24141861, 2013). "This allowed us to verify that association improved for certain genes, such as ADAM33, as recently supported for other firm candidates, and also to gain insight in the genetic complexity of asthma associations at these candidate genes." (PMID 24039878, 2013). "For instance, GWASs have been essential in the discovery of many asthma-associated genes, including disintegrin and metalloproteinase domain-containing protein 33 (ADAM33)." (PMID 22675370, 2012). "ADAM33 SNPs have been associated with airway remodeling and bronchial hyper-responsiveness, but have varying associations with asthma/allergy and total serum IgE across ethnic populations." (PMID 21320344, 2011).